IL15 (interleukin 15)
Diseases named in the same sentence as IL15 in open-access papers (continued):
Sharing a sentence is not in itself a finding about the gene and the disease.
COVID-19 (continued). "Numerous reports have shown that IL-15 is increased in the plasma of COVID-19 patients, suggesting that IL-15 may be a marker of symptomatic progression or mortality." (PMID 36851770, 2023). "In addition, we found significantly elevated IL-15 in plasma from hospitalized COVID-19 patients at equivalent levels to those previously reported." (PMID 36851770, 2023). "The increase in granzyme B levels in NK cells may be partially mediated by pro-inflammatory cytokines actively produced during COVID-19, such as IL-15." (PMID 36768315, 2023). "We also observed a > 2-fold increase in IL-15 in COVID-19 patients (2.3 ± 0.1 for controls vs. 5.7 ± 0.8 pg/mL for COVID-19 patients) and a 10-fold increase in CXCL10/IP-10 over controls (401.5 ± 75.5 pg/mL controls vs. 4257.0 ± 1383.1 pg/mL COVID-19 patients, p < 0.001)." (PMID 36851770, 2023). "The cytokine and chemokine responses to the 1st and 2nd dose of the Pfizer mRNA vaccine in antigen-naive and in previously COVID-19-infected individuals had transient increase in IL-15 and IFN-γ levels early after boost which correlate with Spike antibody levels." (PMID 36814238, 2023). "There are a number of Phase 1 (and some 2a) trials in the pipeline specifically for the implementation of allogenic NK cellular transfer, CAR-NK cells secreting an IL15 superagonist, and anakinra or rhIFNy adjunctives in COVID-19 and sepsis with hyperinflammation." (PMID 36979757, 2023). "Both the activation and differentiation of NK cells may be induced by high levels of IL-15 during COVID-19." (PMID 36768315, 2023). "Thus, we have shown that against the background of COVID-19, under which the concentration of IL-15 increases, T cells acquire the features of innate immune cells." (PMID 37240393, 2023). "Additional monocyte-related mechanisms contributing to NK cell dysfunction may be represented by a reduced secretion of IL-12 and IL-15, two cytokines that sustain NK cell activity and that are markedly reduced in the serum of severe COVID-19 patients." (PMID 35844604, 2022). "Furthermore, filtering our cell-cell interaction data for mechanisms involved in NK-cell differentiation revealed increased IL-15 signaling towards CD8+ T cells in mild COVID-19." (PMID 36591270, 2022). "In our COVID-19 cohort, we observed increased levels of IL-2, IL-4, IL-15, IL17, and IP-10, which likely activate both T-helper-1 (Th1) and T-helper-2 (Th2) cells and lead to lung inflammation and damage, similar to what has been reported in SARS-CoV and MERS-CoV infections." (PMID 36423162, 2022). "Therefore, resistin and IL-15 should be included in the personalized treatment decision algorithm of patients with COVID-19." (PMID 35330391, 2022). "Similarly, alveolar capillary endothelial cells showed strong and diffuse immunoreactivity for IL-6 and IL-15 in the COVID-19 group (p < 0.001)." (PMID 34463916, 2022). "Finally, regarding the prediction of COVID-19 evolution, IL-15 was the best predictor of the necessity of MV and of MV or ECMO plus support with vasopressors and dialysis/renal replacement therapy." (PMID 35330391, 2022). "However, we should further explore the exact molecular mechanism through which albumin and IL-15 worsen survival prognosis in COVID-19." (PMID 34683480, 2021). "We thus investigated whether the use of the IL-15-to-albumin ratio enables improving mortality prediction at hospital admission in a large group of COVID-19 patients." (PMID 34683480, 2021). "In patients with COVID-19, this signature was seen in lung epithelial and NK cells, which is intriguing because airway epithelial cells is a prominent source and the NK cells are a major target of IL15." (PMID 34127431, 2021). "Reports exist of IL-6 and IL-15 upregulation in patients with severe presentations of COVID-19." (PMID 34829906, 2021). "sST2, sTNFRSF1A, IL-10, and IL-15 may differentiate between survivors and patients who die from COVID-19 when measured throughout the entire hospitalization." (PMID 33232303, 2021).
COVID-19 (continued). "To functionally test the role of cytokines on the viability of lymphocytes, we treated PBMCs isolated from healthy donors with selected groups of cytokines (e.g., IL-10, IL-15, IL-18, IL-8, IL-6, IL-1RA, IL-2RA, IL-4) for 36 h, using the maximum doses detected in COVID-19 serum." (PMID 34103487, 2021). "Although albumin measurement appears to be easier than IL-15 quantification in primary care, IL-15 serum levels can be detected quickly and affordably in tertiary healthcare centers, where most patients with severe COVID-19 are admitted." (PMID 34683480, 2021). "One China-based CAR trial initiated in March 2020 employs dual-targeting anti-NKG2D-ACE2 CAR-NK cells, which secretes IL-15 superagonist for NK cell longevity and has a GM-CSF neutralizing receptor to prevent cytokine release syndrome, in COVID-19 patients (NCT04324996)." (PMID 33658994, 2020). "Thus, profound T cell depletion during COVID-19 may similarly affect the T cell compartment for long periods, with increased IL-7 and IL-15 concentrations altering γc receptor levels." (PMID 41310351, 2025). "Therefore, the use of immunomodulatory agents such as IL-15 that may restore the cytotoxic activity in individuals hospitalized due to critical COVID-19 could be useful to help clear the virus from the organism." (PMID 36767310, 2023). "Furthermore, IL-15 is also discussed as a component in immunotherapy in COVID-19 patients." (PMID 36376288, 2022). "Notably, previous studies identified an increase of the proliferating NK cells (high MKI67) with severity of COVID-19 and highlighted the role of IL-15 and TGF beta in the cell state generation, thus emphasising involvement of NK subtypes in COVID-19 pathogenesis." (PMID 36230912, 2022). "SOTRs with COVID-19 have higher plasma levels of cytokines such as IFN-λ1, IFN-γ, IL-15, IL-18 IL-1RA, IL-6, MCP-2, and TNF-α as compared to healthy controls, and the levels of GM-CSF, IL-15, IL-6, IL-8, and IL-10 were associated with disease severity in SOTRs." (PMID 35075453, 2022). "Furthermore, analysis of transcriptomic datasets of host responses to viral infections has revealed that the IL-15/IL-15RA axis plays a role in immune dysregulation, in which prolonged exposure of NK cells to high circulating IL-15 levels in a COVID-19 patient triggers NK cell dysfunction." (PMID 35625739, 2022). "Since the combined use of the IL-15-to-albumin ratio acts as an accurate mortality predictor, we believe that it is of great importance to discuss the possible mechanisms through which these molecules may contribute to the progression and severity of COVID-19." (PMID 34683480, 2021). "Specifically, we found that the expression of genes encoding proinflammatory cytokines (IL12B, IL15, IL6, IL12A and IL1B) and chemokines (CXCL9, CXCL11 and CXCL10) was broadly increased in COVID-19 patients and speculate that other viral infections may also induce expression of these genes." (PMID 33780352, 2021). "Furthermore, we report for the first time a major role of IL-15 in severe COVID-19." (PMID 33317616, 2020). "Pro-inflammatory cytokines, such as IL-5, IL-6, IL-9, and IL-15, were elevated in PLWH/COVID-19 compered to COVID-19-only." (PMID 41516165, 2025). "We and others demonstrated that several cytokines and chemokines including IL‐2, IL‐6, IL‐7, IL‐10, IL-15, IL-17, IP‐10, MCP‐1, TNF‐α, GCSF were related to disease severity and mortality in COVID-19." (PMID 40315230, 2025). "Six chemokines (CXCL9, CXCL10, CCL4, CCL5, CCL27, and CXCL12) and eight interleukins (IL-1Ra, IL-2Ra, IL-3, IL-5, IL-9, IL-12p40, IL-15, and IL-16) were increased in both PLWH/COVID-19 and COVID-19-only." (PMID 41516165, 2025). "This classifier reinforced the prognostic importance of monocyte/macrophage, NK cell, and Th1-pathway activation, with prediction of severe COVID-19 driven by higher concentrations of IL-7, CXCL10, IL-15, and CXCL9, and lower concentrations of MDC and IL-5." (PMID 38368384, 2024).
COVID-19 (continued). "The aim of this study was to analyze the potential relationship between the level of selected cytokines (IL-6, IL-10, IL-12, IL-15, TNF-α) and inflammatory markers (CRP, NLR, PLR, LMR, SII) and the duration of rehabilitation in patients after COVID-19." (PMID 39335569, 2024). "The seven pro-inflammatory cytokines (IL-6, IL-8, IL-15, IL-18, IL-27, IFN-γ, and TNF-α) and two anti-inflammatory cytokines (IL-1RA and IL-10) were elevated in COVID-19 patients compared to healthy controls." (PMID 39408907, 2024). "Recent work has also highlighted likely role of IL-15 in monocytes, along with CD8 T cells, in COVID-19–recovered males leading to higher IFNG and increased in antibody responses after influenza vaccination." (PMID 39331702, 2024). "Our findings indicate that plasma levels of TSLP, IL-15, and CXCL10/IP-10 were elevated in COVID-19 patients over that of normal uninfected controls." (PMID 36851770, 2023). "IL-15 and IFN-g have been reported to correlate with antibody response after the second dose of BTN162b2 mRNA COVID-19 vaccine." (PMID 38235127, 2023). "In male participants, EGF, GM-CSF, IL-1ra, IL-1α, IL-1β, IL-2, IL-4, IL-7, IL-15, EOTAXIN, MDC, MIP-1α, MIP-1β, IFNα2, and sCD40L were significantly lower in COVID-19 patients compared to controls." (PMID 36554094, 2022). "We also described the correlation of inflammatory cytokine levels (resistin, IL-6, IL-8, IL-15, MCP-1 and TNF-α) with clinical variables related to a worse COVID-19 prognosis." (PMID 35330391, 2022). "Since no molecular studies were available for CAM patients, we focused on studies featuring COVID-19 severity and selected nuclear factor erythroid 2-related factor 2 (NRF2), interleukin-6 (IL-6), and IL-15 as the candidate genes for this analysis (30, –, 33)." (PMID 36377893, 2022). "Morphometry-based microscopic analysis revealed that the immunohistochemical reaction generated by antibodies against TNF-α, IL-1β, IL-15, IL-6, MCP-1, CD8, CD20, and CD45 was significantly different between the COVID-19 group and the control group." (PMID 34463916, 2022). "Specifically, ncfDNA was correlated with cytokines/chemokines such as IL-15, IL-8, Eotaxin-3, IL-1β, IL-10, IL-16, VEGF, IL-6, IL-7, GM-CSF and IL-1α in SOTRs with COVID-19." (PMID 35075453, 2022). "We now show that the same ViP signatures can objectively demonstrate the shared immunophenotypes between all three syndromes (COVID-19, KD and MIS-C), which features an upregulation of the IL15/IL15RA pathway." (PMID 35577777, 2022). "Thrombocytopenia, which was more pronounced in MIS-C and correlated significantly with IL15 and IL15/IL15RA composite transcript score in both KD and MIS-C, has also been reported in COVID-19 and postulated because of various mechanisms." (PMID 35577777, 2022). "The levels of the pro-inflammatory cytokines GM-CSF, IL-6, IL-15, and IFN-α were higher in mild-moderate COVID-19, compared to healthy controls, with a further increase in severe COVID-19." (PMID 35529862, 2022). "IL-6, IL-8, IL-10, and TNF-α were increased in severe cases of COVID-19 while IFN-α, IL-1β, IL-4, and IL-15 were enriched in mild cases." (PMID 35685940, 2022). "COVID-19 patients, in comparison to healthy controls, showed six elevated biomarkers (IP-10, NT-proBNP, HGF, MCP-3, IL-15, IL-1RA)." (PMID 35844615, 2022). "IL-15, CCL8, and CXCL10 levels were also significantly elevated in the BAL fluid of patients with COVID-19 in the mid- or late phase of a coinfection compared with patients without coinfections." (PMID 34793331, 2022). "Plasma levels of IL-1RA, IL-10, IL-15, and G-CSF and of the chemokines CCL3, CCL4, CXCL8, and CXCL10 were significantly increased in patients with COVID-19 compared with those of healthy controls." (PMID 34793331, 2022).
COVID-19 (continued). "Moreover, the IL-15 immunotherapy may be a feasible strategy for COVID-19, as it induces innate immune responses via the induction of NK cells, CD8+ T cells, and T regulatory cells to neutralize Th2 cytokine storms, leading to decreased levels of IL-4, IL-5, and IL-13." (PMID 35679246, 2022). "Thus, the ViP signatures begin to paint a picture of ‘paradoxical immunosuppression’ at the heart of fatal COVID-19, in which, the observed NK cell exhaustion/depletion in severe COVID-19 could be a consequence of an overzealous IL15 storm, leading to their senescense and apoptosis." (PMID 34127431, 2021). "Some of these factors, along with PaO2/FiO2 index, the incidence of acute kidney injury (AKIN), co-infections, APACHE-II score, IFN-γ, IL-15, and CCL5, also contributed to differentiate the entire COVID-19 cohort from pandemic influenza A(H1N1) subjects." (PMID 33995342, 2021). "CXCL10, interleukin (IL-15) and interferon (IFN-g) are increased after a COVID-19 vaccination with a BNT162b2 mRNA (Pfizer/BioNTech) vaccine and are enriched by tumor necrosis factor alpha (TNF-α) and IL-6 after the second vaccination." (PMID 34835155, 2021). "This was observed for TGFB3, CCL4, IL15, and IL20RA in both ICM samples vs. COVID-19 samples and NIDCM samples vs. COVID-19 samples." (PMID 34071557, 2021). "Altogether, this information reveals a pivotal role of IL-15 in the progression of SARS-CoV-2 infection and supports using this cytokine as a mortality predictor in COVID-19 patients." (PMID 34683480, 2021). "Thus, IL-15 appears to orchestrate a two-hit deleterious action characterized by an exaggerated inflammatory response and increased endothelial cell apoptosis that together may contribute to the severity of COVID-19." (PMID 34683480, 2021). "When comparing COVID-19 mild vs critical patients, we identified IFNLR1, IFNA1, CXCL9, CXCL10, IL15 and IL15RA to be upregulated in mild patients." (PMID 33473155, 2021). "The prognostic value of IL-6, IL-15, sRAGE, IP10, and MCP3 to predict a poor COVID-19 outcome is consistent with the observation of an exacerbated innate inflammatory response in patients with severe disease." (PMID 34829906, 2021). "Levels of IL-6, IL-10, IL-15, IFN-γ, TNF-α, CCL2, CCL3, CCL4, CCL26, CXCL9 and CXCL10 were significantly elevated both in COVID-19 critical clinical condition and in MAS patients as compared to healthy controls." (PMID 34226537, 2021). "Kidney failure can be mediated via IL-15 and MMP12, which are often involved in monocyte response—a critical part of COVID-19 activation." (PMID 34608231, 2021). "COVID-19 patients had lower levels of most classical inflammatory cytokines (G-CSF, CCL20, IL-1β, IL-2, IL-6, IL-8, IL-15, TNF-α, TGF-β), but higher plasma concentrations of CXCL10, GM-CSF and CCL5, compared to non-COVID-19 patients." (PMID 33272291, 2020). "Increased levels of interleukins (IL-1 α, IL-7, IL-17, and IL-18) and chemokines (CCL11, and CXCL1) were found only in the COVID-19-only, whilst PLWH/COVID-19, had increased levels of four different interleukins (IL-5, IL-6, IL-9, and IL-15) and one chemokine (CXCL10) compared to COVID-19-only." (PMID 41516165, 2025). "The mean IL-7 and IL-15 levels were also only marginally elevated in the vaccinees irrespective of the COVID-19 exposure before or after the vaccination." (PMID 41012170, 2025). "The increased CRP together with elevated IL-6 and IL-15 in PLWH/COVID-19 could indicate hyperinflammation, further explaining the observed differences in the outcome of the COVID-19." (PMID 41516165, 2025). "Haematological, biochemical and cytokine profiles segregate severe from non-severe cases of COVID-19 with an excellent performance of C-RP (AUC = 0.95; p < 0.001) and good performance of lymphocytes (AUC = 0.88; p < 0.001) and IL-15 (AUC = 0.86; p < 0.001)." (PMID 39528988, 2024).
COVID-19 (continued). "Among patients enrolled within 7 days of symptom onset, evidence of pro-inflammatory monocyte/macrophage (IL-1Ra, IL-1β, IL-6, CXCL10), NK cell (IL-15), Th1/Th17-pathway (IL-7, IL-15, IL-17F), and endothelial (VEGF-A) activation were apparent in patients with severe COVID-19." (PMID 38368384, 2024). "Lung samples from COVID-19 autopsies revealed that the inflamed pulmonary endothelium expressed IL-1β, IL-6, IL-15 and TNF-α, in contrast to non-infected tissue samples, recruiting inflammocytes along the alveolar epithelium." (PMID 37568402, 2023). "In a cytokine profile study of COVID-19 patients, lower IL-15 levels distinguished non-survivors from survivors at a particular stage of the disease." (PMID 36768315, 2023). "Further supporting these associations from circulating blood levels, Patients with COVID-19 exhibited elevated IL-18 and IL-15 expression in their lung tissues compared with control patients without COVID-19." (PMID 36894537, 2023). "Previous studies found increased the Th2 cytokine profile (i.e., IL-4 and IL-15) and IL-10 in the blood of recovered mild COVID-19 patients without sequelae." (PMID 37753077, 2023). "IL-6 and IL-15 were not increased in the mild COVID-19 group but were significantly elevated in the moderate and severe groups." (PMID 35663992, 2022). "Our results show that the levels of IL-12p70 are significantly increased in severe COVID-19 survivors compared to non-survivors, as are those of IL-12p40, IL-15 and IL-27." (PMID 36142255, 2022). "Also, the interleukins (IL1B, IL15, IL16, and IL32) were found to be upregulated in the active COVID-19 patients, indicating a T cell and monocyte-mediated proinflammatory response during active COVID-19." (PMID 36532041, 2022). "The levels of IP-10, IL-15, IL-18, and TNF-α were exclusively increased in SOTRs with COVID-19." (PMID 35075453, 2022). "While the levels of IP-10, IL-15 and IL-18 were exclusively increased in SOTRs with COVID-19, Non-SOT patients with COVID-19 showed solely higher levels of IFN-β, IL-2, IL-10, GM-CSF and low levels of Eotaxin, MCP-1, MIP-1β, IL-4, IL-5." (PMID 35075453, 2022). "Pregnant women infected with SARS-CoV-2 had increased systemic concentrations of IL-8 (5.9-fold change (FC)), IL-10 (2.3-FC), and IL-15 (1.5-FC) compared to control mothers; such changes were not driven solely by the severe COVID-19 cases." (PMID 35042863, 2022). "A significant increasing trend of IL-1β, IL-1ra, IL-2, IL-4, IL-5, IL-6, IL-7, IL-8, IL-10, IL-12(p70), IL-15, IL-17, FGF-b, G-CSF, GM-CSF, IFN-γ, IP-10, MCP-1, MIP-1α, PDGF, TNF-α, and VEGF was observed in the three groups (Controls ≤ Mild COVID-19 ≤ Severe COVID-19)." (PMID 34675240, 2021). "In parallel, there is little evidence supporting the possible role of IL-15 in the progression and mortality of COVID-19." (PMID 34683480, 2021). "PIMS-TS children had significantly elevated levels of cytokines, IFNγ, IL-2, TNFα, IL-1α, IFNα, IFNβ, IL-6, IL-15, IL-17A, GM-CSF, IL-10, IL-33 and IL-Ra; elevated chemokines, CCL2, CCL19, CCL20 and CXCL10 and elevated VEGF, Granzyme B and PDL-1 in comparison to COVID-19, seropositive and controls." (PMID 33813138, 2021). "Cytokine-related genes that are dysregulated in both cardiomyopathy patients and COVID-19 patients include chemokines (CCL3, CCL4, CXCL4, etc.), interleukins or interleukin receptors (IL15, IL20RA, etc.), and genes in the transforming growth factor beta (TGFB) family." (PMID 34071557, 2021). "Our findings indicated that patients with severe COVID-19 who progress to ICU admission and/or death are characterized by a markedly disturbed IR, mainly involving elevated serum levels of IL6, IL15, sIL1RII, sRAGE, IP10 and MCP3 in the first week of hospitalization." (PMID 34829906, 2021).